TBC1D10C (TBC1 domain family member 10C)
Description:
Inhibits the Ras signaling pathway through its intrinsic Ras GTPase-activating protein (GAP) activity. Acts as a negative feedback inhibitor of the calcineurin signaling pathway that also mediates crosstalk between calcineurin and Ras.
Synonyms: FLJ00332; Carabin; EPI64C
Tractability: Antibody: its Gene Ontology location is reachable by antibodies, with high confidence. PROTAC: ubiquitination databases record sites on it; its protein half-life has been measured.
Gene: Protein-coding gene on chromosome 11 (67,398,454 to 67,410,092, forward strand). Ensembl gene ENSG00000175463.
Subcellular location (Human Protein Atlas): Nuclear bodies
Pathways (Reactome):
Immune System: Neutrophil degranulation
Vesicle-mediated transport: TBC/RABGAPs
Gene Ontology:
Molecular function: protein binding; GTPase activator activity
Biological process: regulation of cilium assembly; retrograde transport, endosome to Golgi
Cellular component: filopodium membrane; membrane; plasma membrane; ficolin-1-rich granule membrane; cytosol
Genetic constraint (gnomAD): Loss-of-function variants: 50 observed, 47.66 expected, observed/expected ratio (o/e) 1.05, 90% interval 0.83 to 1.33. The upper end of that interval is the gene's LOEUF score, 1.33, which puts it in group 5 of 6, group 1 being the genes least tolerant of losing a copy. Missense variants: 541 observed, 556.3 expected, observed/expected ratio (o/e) 0.97, 90% interval 0.9 to 1.04. Synonymous variants: 281 observed, 237.03 expected, observed/expected ratio (o/e) 1.19, 90% interval 1.08 to 1.31.
Homologues: Orthologues: chimpanzee TBC1D10C (99% identical), macaque TBC1D10C (99% identical), dog TBC1D10C (93% identical), pig TBC1D10C (92% identical), guinea pig TBC1D10C (91% identical), rabbit TBC1D10C (89% identical), rat Tbc1d10c (89% identical), mouse Tbc1d10c (88% identical), zebrafish tbc1d10c (43% identical). Paralogues in human: TBC1D10A (46% identical), TBC1D10B (45% identical), EVI5L (26% identical), EVI5 (26% identical), TBC1D8 (26% identical), TBC1D9B (26% identical), TBC1D9 (25% identical), RABGAP1L (24% identical), TBC1D1 (24% identical), TBC1D2 (24% identical), RABGAP1 (24% identical), TBC1D8B (23% identical), and 33 more.
Diseases named in the same sentence as TBC1D10C in open-access papers:
TBC1D10C is named in the same sentence as 11 diseases in open-access papers, as found by Europe PMC text mining. Sharing a sentence is not in itself a finding about the gene and the disease. The quoted sentences say what the papers report.
melanoma (3 papers, 2020 to 2023). A malignant, usually aggressive tumor composed of atypical, neoplastic melanocytes. "Seven prognosis associated TBCs genes including TBC1D13, TBC1D16, TBC1D7, TBC1D10C, TBC1D19, TBC1D8B, and TBC1D15 were identified in melanoma." (PMID 33194704, 2020). "CYTH4, DENND1C, AOAH, TBC1D10C, EPSTI1, GIMAP7, and FASL (FAS ligand) were novel predictors of ICB therapy and displayed high level of correlations with multiple immune checkpoints in melanoma and across 30 human cancers." (PMID 36588164, 2023).
atherosclerosis (1 paper, 2025). A disease characterized by the build-up of fatty material and calcium deposition in the arterial wall resulting in partial or complete occlusion of the arterial lumen. "Given that TBC1D10C functions as an autophagy inhibitor, it can be deduced that TBC1D10C contributes to the risk factors associated with atherosclerosis." (PMID 41031220, 2025).
renal carcinoma (1 paper, 2025). A carcinoma arising from the epithelium of the renal parenchyma or the renal pelvis. "Nine intersecting genes were screened and used to construct a prognostic model, whereby seven key biomarkers—MXD3, PLCB2, CCDC88B, DEF6, IFNG, TBC1D10C, and PLEKHN1—were significantly influenced the prognosis of renal cancer." (PMID 41357186, 2025).
tumor (3 papers, 2020 to 2024). "We also identified a hub gene, TBC1D10C, which was correlated with both OS and the PFI and had a high positive association with tumor-infiltrating immune cells and common immune checkpoints." (PMID 35425695, 2022). "Subsequently, we identified a hub gene, TBC1D10C, that correlated with OS and the PFI and had a high positive association with tumor-infiltrating immune cells and three common immune checkpoints (PD-1, CTLA-4, and TIGIT)." (PMID 35425695, 2022). "TBC1D10C protein is an inhibitor of both the Ras signaling pathway and calcineurin, and is reported to be related to the immune response, inflammatory response and formation of the tumor microenvironment." (PMID 32831060, 2020).
cancer (2 papers, 2023). A tumor composed of atypical neoplastic, often pleomorphic cells that invade other tissues. "Though the functions of C16orf54, RARRES3, and TBC1D10C in cancer development have also been previously studied, their roles in NPC are revealed for the first time in this study." (PMID 37766321, 2023). "Additionally, CYTH4, DENND1C, AOAH, EPSTI1, and TBC1D10C exhibit strong correlations with a set of immune checkpoints not only in SKCM but also across a spectrum of human cancers." (PMID 36588164, 2023). "CYTH4, AOAH, DENND1C, TBC1D10C, EPSTI1, SERPINB8, and GIMAP7 are novel and robust individual genes in predicting resistance to ICB in multiple cancer types." (PMID 36588164, 2023).
TBC1D10C also shares sentences with these, for which no sentence is quoted: Autoimmunity (1 paper); breast carcinoma (1); glomerulonephritis (1); lupus- (1); sarcoma (1); skin cutaneous melanoma (1).